SSU72L3 (SSU72 like 3)
Description:
Protein phosphatase that catalyzes the dephosphorylation of the C-terminal domain of RNA polymerase II. Plays a role in RNA processing and termination.
Synonyms: SSU72P3
Gene: Protein-coding gene on chromosome 11 (4,329,790 to 4,330,864, forward strand). Ensembl gene ENSG00000284546.
Subcellular location: Nucleus
Gene Ontology:
Molecular function: protein serine/threonine phosphatase activity; RNA polymerase II CTD heptapeptide repeat phosphatase activity; phosphoprotein phosphatase activity
Biological process: termination of RNA polymerase II transcription; mRNA 3'-end processing; mRNA processing; regulation of transcription by RNA polymerase II
Cellular component: mRNA cleavage and polyadenylation specificity factor complex; nucleus
Homologues: Orthologues: tropical clawed frog ssu72 (68% identical), zebrafish ssu72 (68% identical), Drosophila melanogaster Ssu72 (49% identical), Caenorhabditis elegans ssup-72 (46% identical). Paralogues in human: SSU72L4 (98% identical), SSU72L5 (98% identical), SSU72L1 (97% identical), SSU72L2 (96% identical), SSU72L6 (93% identical), SSU72 (72% identical).